BARD1 (BRCA1 associated RING domain 1)
Diseases named in the same sentence as BARD1 in open-access papers (continued):
Sharing a sentence is not in itself a finding about the gene and the disease.
tumor (continued). "Within the TCGA, there are six tumours with BARD1 amplification and two with missense mutations of unknown significance." (PMID 34680387, 2021). "Since BARD1-FL acts as a tumor suppressor, these studies suggest that the BARD1 they are detecting is likely mutated or a splicing variant, however, more research needs to be conducted to classify the isoforms of BARD1 that play an oncogenic role in HCC." (PMID 32708251, 2020). "Moreover, in the 2p35 region, within BARD1, several SNPs have been identified and associated with a more aggressive tumor behavior." (PMID 30791380, 2019). "A triple-negative tumor phenotype was reported for 4 of 20 BARD1-mutated index patients with BC." (PMID 31036035, 2019). "In this study, we identified 76 BARD1 missense and truncation variants that were potentially cancer-associated from a large dataset containing exome-sequencing data on matched germline and tumor samples, and tested them for HDR function." (PMID 30925164, 2019). "We therefore concluded the mutations and epigenetic modifications in BARD1 gene may lead to the loss of tumor-suppressor function and further favor the HCC carcinogenesis." (PMID 28794477, 2017). "Furthermore, a tumor-associated germline mutation in BARD1 (Gln564His) decreases its affinity for CSTF-50 and renders the protein inactive in polyadenylation inhibition." (PMID 27220521, 2016). "Interestingly, the polyadenylation factor CstF associated to the tumor suppressors BRCA1/BARD1 play a role in the proteasome-mediated degradation of POLR2A during DDR." (PMID 27462460, 2016). "Interestingly, and consistent with its function as a tumor suppressor, the loss of FL BARD1 (Full Length BARD1) in favor of mutated variants is a commonly reported event in solid cancers." (PMID 24349422, 2013). "Interestingly, BARD1 is itself a tumor suppressor, mutations of which have been linked to breast, ovarian, and endometrial cancers." (PMID 23802008, 2013). "Importantly, tumor-associated mutation in the RING-finger domain of BRCA1 abolishes the ubiquitin ligase activity of the BRCA1/BARD1 complex, suggesting a strong connection between BRCA1's E3 ligase activity and its tumor suppressor function." (PMID 21217819, 2010). "Mutations outside BARD1’s canonical functional domains may also impact tumor suppressor activity." (PMID 41009605, 2025). "Given the phospho-dependent interaction of p50 with BARD1, it would be interesting not only to examine p50 in these mice, but also to evaluate whether they have altered susceptibility to carcinogen-induced tumor formation, as was previously seen with Nfkb1-/- mice." (PMID 33024116, 2020). "Moreover, we identify a specific BARD1 isoform, which might act as tumor diagnostic and prognostic markers." (PMID 24349422, 2013). "Moreover, we identified specific BARD1 isoforms that might act as oncogenes and as tumor diagnostic and prognostic markers." (PMID 24349422, 2013). "Thus, the three overexpressed truncated BARD1 mRNA isoforms, together with FL BARD1 down-regulation, might be bona fide candidates as diagnostic tumor markers." (PMID 24349422, 2013).
tumor (continued). "These discordant roles emphasize that BARD1 isoform function is highly context-dependent and shaped by isoform-specific structure and tumor type, and, therefore, requires careful evaluation of its cell-specific activities." (PMID 41009605, 2025). "The cellular levels of BARD1 and its interaction with BRCA1 are critical for the heterodimeric function of the BRCA1-BARD1 complex in HR repair and tumor suppression." (PMID 41009605, 2025). "Treatment with the DNA methyltransferase inhibitor 5′-azacytidine in combination with a murine anti-VEGF antibody significantly restored BARD1 expression and reduced tumor burden in multiple in vivo models." (PMID 41009605, 2025). "SIRT2, in particular, has been shown to deacetylase BARD1 at conserved lysine residues within the RING domain, promoting stability of the BRCA1-BARD1 complex and enabling tumor-suppressive function." (PMID 41009605, 2025). "Further, BARD1 silencing was found to significantly reduce colony formation, cell proliferation, and invasion in vitro and slow tumor growth in vivo in mouse xenografts." (PMID 41009605, 2025). "Mechanistically, many pathogenic BARD1 variants impair HR, underscoring a critical role in the impairment of BARD1’s tumor suppressor functions." (PMID 41009605, 2025). "LOH-CNN, indicating wild-type allele loss with amplification of tumour suppressor losses, was observed in BCL2L11 and BARD1 for patients KAL0101 and N0073." (PMID 40064858, 2025). "BARD1 (BRCA1-associated RING domain protein 1) on chromosome 2q34-q35 interacts with BRCA1 to participate in DNA damage repair and tumor suppression." (PMID 41395620, 2025). "The single nucleotide resolution allowed discrimination of variant effects on RNA abundance from those affecting protein function and provided further evidence linking BARD1’s function in homology directed repair to tumor suppression." (PMID 41282735, 2025). "The BRCA1 Associated RING Domain protein, BARD1 [OMIM 601593], is required for the BRCA1 tumor suppressor to fold and function." (PMID 41282735, 2025). "Tumor-suppressor genes, including APC, BARD1, HMMR (RHAMM), KLLN, LZTR1, MCPH1 (BRIT1), MLH1, NF1, RB1CC1 (FIP200), SLC22A18, and SPTBN1, have been found to increase the risk of disease and tumor development." (PMID 40941673, 2025). "All together, our identification of functionally critical BARD1 residues demonstrates that BARD1’s role in HDR is critical for tumor suppression, highlighting SGE’s ability to link specific cellular functions to disease." (PMID 41282735, 2025). "BARD1 is a tumor‐related gene that interacts with BRCA1, forming a complex with E3 ubiquitin ligase." (PMID 39865406, 2025). "Comparison of SGE results to these structures suggests that cell fitness and tumor suppression depend on BARD1’s ability to interact with the nucleosome and read H4K20me0 in newly replicated chromatin and DNA-damage-induced H2AK13ub/K15ub marks." (PMID 41282735, 2025). "Tumor cells that were are refractory to PARPi (abbreviated as “PARPi-Res” in the figure) from both PARPi-treated Brca1-def and Bard1-def tumors were then isolated, re-injected into the mammary glands of new B6/129F1 recipient mice and treated." (PMID 38956205, 2024).
tumor (continued). "Up to date, the relevance of the BRCA1/BARD1 E3 activity for DSBs repair, tumor suppression, and resistance to PARP inhibitors and platinum-based compounds is still controversial." (PMID 38769345, 2024). "Two tumours harboured a private non-synonymous mutation in the HR-DDR pathway genes ATM and BARD1, respectively." (PMID 39020404, 2024). "Wild-type BARD1 is known to function as a tumor suppressor through pathways that are BRCA1-dependent and independent." (PMID 39233942, 2024). "The relevance of the BRCA1/BARD1 ubiquitin E3 activity for tumor suppression and DNA repair remains controversial." (PMID 38769345, 2024). "Next, PARPi-resistant Brca1-def and Bard1-def tumor cells, transduced with either control lentivirus (“Lenti-Con”), Flt1i lentivirus, or Flt1i lentivirus plus Flt1 o/e lentivirus, were injected orthotopically in the mammary glands of syngeneic B6/129F1 mice." (PMID 38956205, 2024). "We initially compared the total expression levels of ERBB2, RAD21, RAD50 and BARD1 mRNA in normal and tumor bladder tissues with bioinformatics analyses using the TCGA database (Cohort one)." (PMID 37474724, 2023). "HR-E6 also interacts with BRCA1 and BARD1 (BRCA1 Associated RING Domain 1) ubiquitin ligases, which also serve as tumor suppressors." (PMID 38005929, 2023). "BARD1 has homology BRCT domain of BRCA1, and the stable interaction between BRCA1 and BARD1 is essential for BRCA1 as a tumor suppression." (PMID 36593954, 2023). "The search on Medline gave 14 results, of which 3 were excluded: one was a discussion about tumour histology, one was an erratum (author name spelling error), and one was regarding a different gene (BARD1)." (PMID 38146508, 2023). "Highly mutated genes like BARD1, MALT1, BRCA1/BRCA2, EIF3K, PTEN, FGFR2, and MAP3K1 were also found to overlap with SVs of the tumor sample that were identified by one or more technologies in our study." (PMID 36514120, 2022). "BRCA1/BARD1 also contributes to tumor suppression via the ubiquitination pathway and subcellular localization of BRCA1." (PMID 35650591, 2022). "Although BRCA1 requires BARD1 for stability and tumor suppressor functions, BARD1 also plays distinct roles in cell cycle progression." (PMID 35084436, 2022). "Among 100 tumor-normal pairs sequenced, somatic mutations of 1p tumor suppressors KIF1Bβ and CHD5 were most frequent (2%) after ALK and ATRX (8%), and BARD1 (3%)." (PMID 35768791, 2022). "NG tumor samples not only possessed comparable rates of gene-level variation [BRCA1 (100%), BARD1 (41%), and BRCA2 (18%)] but also showed comparable variant frequencies." (PMID 36922933, 2022). "All these functions support the tumor suppressor role of the FL-BARD1 in contrast, BARD1 isoforms such as BARD1 β and BARD1 δ were reported to oppose this function and further promote cancer progression." (PMID 35650591, 2022). "Other mutational variants associated with increased tumor proliferation and poor outcome include LIN28B, BARD1 and LMO1." (PMID 35768791, 2022). "BARD1 displays a dual role in cancer development and progression as it acts as a tumor suppressor and an oncogene." (PMID 35650591, 2022). "The differences in BARD1 expression depend on the histological type of neoplasm, and the level of maturation in neuroblastic tumours." (PMID 33530592, 2021). "Our results indicated a highly probable function of BARD1 and its isoforms in other childhood tumours’ pathobiology; however, it needs to be verified in a larger cohort of patients." (PMID 33530592, 2021). "The full-length BARD1 is classified as a tumour suppressor and the main partner of BRCA1 (forming a heterodimer via the RING domain)." (PMID 33530592, 2021).
tumor (continued). "Dimerisation of BRCA1 and BARD1 is required to stimulate their shared ubiquitination activity and is required for the heterodimer tumour suppressor functions." (PMID 33672422, 2021). "The present study aimed to assess the expression of BARD1 FL and BARD1 β indifferent pediatric tumours." (PMID 33530592, 2021). "A possible explanation is a link between neural crest differentiation, maturing morphology in NB tumours and a role of BARD1 isoforms in these processes; however, this phenomenon needs further evaluation." (PMID 33530592, 2021). "Full length (FL) BARD1 is a tumour-suppressor gene playing an essential role in cell cycle control and genome stability." (PMID 33530592, 2021). "Molecular biology studies have demonstrated that BARD1 can affect cell growth and tumour suppressor activity and play a role in neoplasia." (PMID 34680387, 2021). "The expression of BARD1 isoforms was widely studied in several adult type malignancies, such as colorectal, lung, and gynaecological cancers, whereas its role in pediatric tumours is yet to be discovered." (PMID 33530592, 2021). "Compared to adjacent tissue, there is a decreased proportion of nuclear/cytoplasmic BARD1 in tumor samples, indicating the specific upregulation of cytoplasmic BARD1 in BC tissues." (PMID 34789768, 2021). "In support of BARD1 as a tumor suppressor, rs7585356 leads to the overexpression of BARD1-FL while rs1048108 does not affect BRCA1 binding." (PMID 32708251, 2020). "The BARD1 gene is located on chromosome 2q35 and encodes a protein that interacts with the N-terminal region of BRCA1 and acts as a tumor suppressor creating a BRCA1/BARD1 heterodimer with ubiquitin E3 ligase activity." (PMID 32046255, 2020). "p50wt reduced tumor size compared to empty vector, but p50DE2A did not, indicating that the propensity of p50 to restrict tumor growth was mediated by its ability to bind BARD1." (PMID 33024116, 2020). "In this review, we focus on the function of BARD1 in centrosome regulation and its role as a tumor suppressor together with BRCA1/OLA1/RACK1." (PMID 32722046, 2020). "Although FL BARD1 expression can have oncogenic effects 17-20, its role as tumor suppressor remains to be elucidated." (PMID 32047556, 2020). "BARD1 was undetected in normal healthy controls, suggesting that BARD1 and its isoforms play a key role in cellular transformation and tumor progression in the lung." (PMID 32708251, 2020). "Whereas BARD1, BLM, and RAD51D mutations have a possible ethnic association, we identified only partial support for tumor and family member associations due to the limited sample size." (PMID 32566746, 2020). "Given this link between endogenous p50 and BARD1, we next looked at these two proteins in clinical tumor specimens using immunohistochemistry (IHC)." (PMID 33024116, 2020). "In summary, BARD1-FL acts as a tumor suppressor in the development of NB, primarily by regulating DDR, cellular proliferation, and programmed cell death." (PMID 32708251, 2020). "In particular, BAP1 is thought to bind to the breast cancer type 1 susceptibility protein (BRCA1) and the BRCA1-associated RING domain protein 1 (BARD1) and enhance their tumor suppressor function." (PMID 32226777, 2020). "LOH or AST mutation was detected in at least one tumor with PALB2, ATM, RAD51D, BARD1, BRIP1, RAD51C, or NF1 germline mutation." (PMID 32566746, 2020). "We demonstrated a role for FL BARD1 as tumor suppressor to prevent unscheduled mitotic entry of DNA damaged cells and to lead to death cells that have bypassed cell cycle checkpoints." (PMID 32047556, 2020). "Molecular biology studies of BARD1 support a role in neoplasia in modifying cell growth and tumour suppressor activity leading to tumourigenesis, particularly in the context of modelling variants found associated with heritable disease." (PMID 32726901, 2020).
tumor (continued). "Rad50, Rad51, Rad54b, Mre11a, Palb2, Brca1 and Bard1 all showed significantly higher expression in resistant tumours compared to responding tumours (p = 0.05, p < 0.001, p < 0.001, p < 0.001, p = 0.002, p < 0.001 and p = 0.012 respectively)." (PMID 31080552, 2019). "The BAP1 protein contains binding domains for BRCA1 and BARD1, enzymes that form a heterodimeric complex that functions as a tumor suppressor." (PMID 31382494, 2019). "Analysis from the tumor sequencing data indicated BARD1 S339T, T343I, V523A, N450H, G451fs, and L239Q had significantly increased LOH, suggesting that these variants were more likely to be pathogenic." (PMID 30925164, 2019). "A set of data demonstrated that somatic mutations and/or predisposition gene silencing variants can be associated with dysregulation of full-length BARD1 (FL BARD1), which can be taken into attention as an early hit of BARD1 tumor suppressor function." (PMID 30975222, 2019). "All these observations, together with our results, suggest that, in the absence of the BRCA1-UbcH5a complex, the maintenance of the binding with BARD1 is dispensable for the BRCA1 tumor suppressor activity." (PMID 30696104, 2019). "BARD1 BRCT performs tumor suppressor function by recruiting BRCA1 at DNA damage site via interactions with other DNA damage repair (DDR) proteins." (PMID 35548793, 2018). "Emerging data suggest that BARD1 can have both tumor-suppressor gene and oncogene functions in tumor initiation and progression." (PMID 29292755, 2017). "BARD1 epitopes were first described as tumor antigens in a screen for tumor antigens in a murine mouse model." (PMID 28786985, 2017). "Bound to BRCA1, BARD1 is an essential component of BRCA1’s tumor suppressor activity due to the E3 ubiquitin ligase activity of the BRCA1-BARD1 heterodimer." (PMID 28786985, 2017). "BAP1 encodes a nuclear ubiquitin carboxyterminal hydrolase, which is a class of deubiquitinating enzymes, and contains binding domains for BRCA1 and BARD1 to form a tumor suppressor complex among other functions." (PMID 28302097, 2017). "The over-expression of BARD1 isoforms was strongly correlated with tumor progression, specifically in non-small-cell lung cancer (NSCLC)." (PMID 28786985, 2017). "Previous reports have shown that expression of BARD1δ, a deletion-bearing isoform of BARD1, correlates with tumor aggressiveness and progression." (PMID 28030839, 2017). "In the following review, we have focused on the genetic and molecular mechanisms of the dualistic role of BARD1 as oncogene and tumor-suppressor in cancer." (PMID 29292755, 2017). "As isoforms of BARD1 have internal deletions, they are likely to fold differently than FL BARD1 and present tumor antigens." (PMID 28786985, 2017). "Several reports show that BARD1 has an additional BRCA1-independent tumor suppressor function in cancer that is antagonized by the expression of BARD1 isoforms." (PMID 29292755, 2017). "Consistently, BRCA1 complexed with BARD1 has tumor suppression properties and is involved on protein ubiquitination for degradation." (PMID 23408952, 2013). "It would be extremely interesting to identify the ubiquitin ligase mediating BRCA1/BARD1 downregulation, as well as to determine how defects in this pathway affect tumor suppressor function." (PMID 21103343, 2010). "BRCA1 participates in multiple cellular supercomplexes to execute its tasks and, in most of the complexes, BRCA1 exists as a RING heterodimer with BARD1 to provide ubiquitin E3 ligase activity that is required for its tumor suppressor function." (PMID 18179693, 2008). "Notably, BRCA1 partners with BARD1 and additional tumor-suppressor proteins to exert critical functions in DNA repair, replication-fork maintenance, and tumor suppression." (PMID 41463377, 2025).